TMEM14C (transmembrane protein 14C)
Description:
Required for normal heme biosynthesis.
Synonyms: C6orf53; HSPC194; bA421M1.6; NET26; MSTP073
Tractability: Antibody: UniProt predicts a signal peptide or a membrane-spanning region. PROTAC: its protein half-life has been measured.
Gene: Protein-coding gene on chromosome 6 (10,722,915 to 10,731,132, forward strand). Ensembl gene ENSG00000111843.
Subcellular location: Mitochondrion membrane
Gene Ontology:
Molecular function: protein binding
Biological process: heme biosynthetic process
Cellular component: mitochondrion; mitochondrial membrane; membrane
Genetic constraint (gnomAD): Loss-of-function variants: 13 observed, 14.46 expected, observed/expected ratio (o/e) 0.9, 90% interval 0.58 to 1.43. The upper end of that interval is the gene's LOEUF score, 1.43, which puts it in group 5 of 6, group 1 being the genes least tolerant of losing a copy. Missense variants: 121 observed, 122.13 expected, observed/expected ratio (o/e) 0.99, 90% interval 0.85 to 1.15. Synonymous variants: 47 observed, 46.18 expected, observed/expected ratio (o/e) 1.02, 90% interval 0.81 to 1.3.
Homologues: Orthologues: chimpanzee TMEM14C (100% identical), guinea pig TMEM14C (87% identical), mouse Tmem14c (85% identical), rat Tmem14cl1 (83% identical), zebrafish tmem14ca (67% identical), zebrafish tmem14cb (49% identical), Drosophila melanogaster CG5532 (48% identical). Paralogues in human: TMEM14B (75% identical), TMEM14A (47% identical).
Diseases named in the same sentence as TMEM14C in open-access papers:
TMEM14C is named in the same sentence as 10 diseases in open-access papers, as found by Europe PMC text mining. Sharing a sentence is not in itself a finding about the gene and the disease. The quoted sentences say what the papers report.
breast carcinoma (3 papers, 2015 to 2017). "CD79A, SERPINH1, KCNJ5 and TMEM14C exhibited breast cancer subtype–independent overall survival differences." (PMID 25572802, 2015).
anemia (2 papers, 2015 to 2022). A reduction in the number of red blood cells, the amount of hemoglobin, and/or the volume of packed red blood cells. "Tmem14c genetrap mice die of anemia at approximately E14.5, when definitive erythropoiesis becomes required for continued embryonic development, and Tmem14c deficient erythroid cells exhibit developmental and metabolic defects." (PMID 35832791, 2022). "Whereas TMEM14C was identified to coexpress with the core machinery of heme biosynthesis and its knockdown causes anemia in zebrafish, TMEM14A was described to stabilize mitochondrial membrane potential and thereby inhibit apoptosis in a yeast system." (PMID 25646734, 2015).
myeloid malignancies (1 paper, 2023). "Interestingly, in a phase I clinical trial using H3B-8800 to treat myeloid malignancies (NCT02841540), aberrant expression of an alternatively spliced isoform of TMEM14C identified patients with good responses." (PMID 37562845, 2023).
sideroblastic anemia (1 paper, 2023). "Moreover, in contrast to canonical SF3B1 mutations, E592K induces a unique RNA missplicing pattern, retains an interaction with the splicing factor SUGP1, and preserves normal RNA splicing of the sideroblastic anemia genes TMEM14C and ABCB7." (PMID 37090662, 2023).
cancer (5 papers, 2015 to 2025). A tumor composed of atypical neoplastic, often pleomorphic cells that invade other tissues. "In addition, siRNA-mediated silencing of all transcripts of eight genes that showed a consistent differential splicing signature across multiple cancer types (ABCC5, ANKHD1, DYNLL1, F8, RPL31, TMEM14C, UQCC, and CRNDE) failed to reveal differences in cell viability." (PMID 25424858, 2015).
TMEM14C also shares sentences with these, for which no sentence is quoted: tumor (2 papers); uveal melanoma (2); chronic lymphocytic leukemia (1); invasive breast carcinoma (1); papillary carcinomas of the breast (1).